WDR62 (WD repeat domain 62)
Diseases named in the same sentence as WDR62 in open-access papers (continued):
Sharing a sentence is not in itself a finding about the gene and the disease.
Tetralogy of Fallot (1 paper, 2022). A congenital cardiac malformation comprising pulmonary stenosis, overriding aorta, ventricular septum defect, and right ventricular hypertrophy. "Exome‐wide association analysis between 37 tetralogy of Fallot (TOF) patients and 208 Han Chinese controls from the 1000 Genomes Project was performed to identify the novel candidate gene WD repeat‐containing protein 62 (WDR62)." (PMID 35808830, 2022).
triple-negative breast carcinoma (1 paper, 2021). An invasive breast carcinoma which is negative for expression of estrogen receptor (ER), progesterone receptor (PR), and human epidermal growth factor receptor 2 (HER2). "More importantly, we observed that WDR62 expression in triple-negative breast cancer (TNBC) was higher than that in other subtypes, suggesting that a distinct mechanism may exist for WDR62 in BRCA subtypes." (PMID 34306258, 2021).
ventricular septal defect (1 paper, 2022). The presence of a defect (opening) in the septum that separates the two ventricles of the heart. "A total of 25 coding and 22 non‐coding WDR62 variants were identified in 80 (6%) of the 1320 CHD cases sequenced, with a higher proportion of WDR62 variation (8%) found in the ventricular septal defect (VSD) cohort." (PMID 35808830, 2022).
Wilms tumor (1 paper, 2013). An embryonal neoplasm characterized by the presence of epithelial, mesenchymal, and blastema components. "The diagnosis of a Wilms tumor in association with a putative WDR62 mutation raises concerns regarding a potentially increased cancer risk in MCPH2 patients also." (PMID 24228726, 2013).
cancer (13 papers, 2013 to 2025). A tumor composed of atypical neoplastic, often pleomorphic cells that invade other tissues. "WDR62 is a protein-coding gene that is implicated in the carcinogenesis of various cancers, including CRC." (PMID 40585306, 2025). "WDR62 is overexpressed in a variety of malignant tumors and is closely associated with tumor occurrence, development, as well as patient survival and prognosis." (PMID 40369663, 2025). "Previous studies have shown that WDR62 can be used as a diagnostic and prognostic biomarker for various cancers, and it is closely associated with infiltration by various immune cells." (PMID 35958927, 2022). "Our pan-cancer study provided useful information on the oncogenic role of WDR62, contributing to further exploring the underlying mechanisms." (PMID 34306258, 2021). "WDR62 expression was associated with various immune cell infiltrations, especially cancer-associated fibroblasts (CAF) and T cell regulatory (Treg) cells, and was markedly correlated with poor prognosis." (PMID 34306258, 2021). "Our study revealed that WDR62 could serve as a diagnostic and prognostic biomarker for several cancers." (PMID 34306258, 2021). "In brief, our first pan-cancer analysis of WDR62 suggested that WDR62 was overexpressed in multiple tumors and closely correlated with poor prognosis and immune regulation, contributing to understanding the oncogenic role of WDR62 across human tumors." (PMID 34306258, 2021). "In order to figure out the oncogenic role of WDR62, we performed a pan-cancer analysis from the view of overall tumors based on bioinformatic data." (PMID 34306258, 2021). "Thus, WDR62 can be considered as a potential biomarker for the detection and differentiation grade of various cancers." (PMID 33937237, 2021). "However, the oncogenic role of WDR62 in other cancers remains unknown." (PMID 34306258, 2021). "Emerging studies support the oncogenic role of WD repeat domain 62 (WDR62) in few tumors, while no pan-cancer analysis is available." (PMID 34306258, 2021).
tumor (10 papers, 2013 to 2025). "High WDR62 expression was strongly associated with supernumerary centrosome count in tumor cells (P < 0.001)." (PMID 23898938, 2013). "Moreover, WDR62 downregulation in tumor cells (HeLa) was associated with spindle orientation defects, decreased centrosome integrity and displacement from the spindle pole as well as delayed mitotic progression." (PMID 24228726, 2013). "Previous evidence indicates that the expression of the host gene WDR62 is significantly upregulated in most tumours and correlates with poor prognosis in multiple cancers." (PMID 35817771, 2022). "At tumor onset we treated the mice with doxycycline to induce WDR62 knockdown and observed that WDR62 is required for tumor growth in vivo." (PMID 34326322, 2021). "Our present study suggests that WDR62 overexpression is an important molecular change specifically related to OC with centrosome amplification, which seems to play a role in both tumor initiation and progression." (PMID 23898938, 2013). "WDR62 promotes tumor growth and resistance to oxaliplatin, and enhances DNA repair in CRC cells." (PMID 40585306, 2025). "What about the effect of WDR62 expression on the prediction for immunotherapy in other tumor types?" (PMID 34306258, 2021). "Accordingly, we considered that WDR62 may play vital roles in tumorigenesis by regulating the tumor microenvironment (TM)." (PMID 34306258, 2021). "Subsequently, our research indicated that WDR62 could also serve as a prognostic biomarker mainly in 6 tumor types." (PMID 34306258, 2021). "Moreover, we observed a correlation between WDR62 expression and the pathological stages of tumors, contributing to the diagnosis of tumor stage." (PMID 34306258, 2021). "Collectively, these results demonstrated that WDR62 may indeed be involved in tumor immune regulation." (PMID 34306258, 2021). "The results showed that the expression of PCBP1-AS1, FAM222A, FHAD1, WDR62, and SBK1 was significantly correlated with tumor clinical stage, pathologic TNM, and lymphatic invasion (p < 0.05)." (PMID 33833992, 2021). "Given that exosomes exhibit their property in intercellular communication between tumor cells and tumor microenvironment, we inferred that the regulatory effect on CAF or Treg cells may be by means of exosomal WDR62." (PMID 34306258, 2021). "There is also a strong positive correlation between WDR62 expression and MKI67, a marker of cell proliferation in mCRPC samples suggesting WDR62 could drive tumor cell proliferation or survival." (PMID 34326322, 2021). "We first compared the expression differences of MAPT, WDR62, PLK1, CDCA8 and TOP2A in normal hepatocyte tissues and HCC tissues by TCGA database, and the results showed that the expression levels of MAPT, WDR62, PLK1, CDCA8 and TOP2A were significantly higher in tumour cells than in normal tissues." (PMID 39072983, 2024).
neurodevelopmental disorder (4 papers, 2014 to 2026). A behavioral and cognitive disorder with onset during the developmental period that involves impaired or aberrant development of intellectual, motor, or social functions. "WES and subsequent filtering of the rare variants in a single affected family member led to the rapid and cost-effective identification of a novel homozygous frameshift mutation in WDR62, thereby explaining the severe neurodevelopmental disorder in this family and facilitating genetic counseling." (PMID 24479948, 2014).
neurological disorders (4 papers, 2021 to 2023). "In addition to homozygous causal variants in ASPM or CENPJ, we discovered additional heterozygous modifier variants in WDR62, CEP63, RAD50 and PCNT—genes already known to be associated with neurological disorders." (PMID 34068194, 2021). "However, whether RA is involved in WDR62-mediated brain development and neurological diseases is currently unclear." (PMID 36571716, 2023).
female reproductive diseases (1 paper, 2021). "Zhou found that inactivation of WDR62 could cause defects in female meiotic initiation, which led to the occurrence of female reproductive diseases." (PMID 33833992, 2021).
WDR62 also shares sentences with these, for which no sentence is quoted: epilepsy (3 papers); Intellectual disability (3); colorectal cancer (2); hepatocellular carcinoma (2); Pachygyria (2); polymicrogyria (2); Alzheimer disease (1); Anxiety (1); brain disorder (1); breast invasive carcinoma (1); coloboma (1); congenital heart disease (1); depression (1); dyskeratosis congenita (1); Fanconi anemia (1); Hepatitis (1); Hoyeraal-Hreidarsson syndrome (1); leukemia (1); Macrocephaly (1); major depressive disorder (1); megalencephaly (1); metastatic disease (1); microphthalmia (1); pancreatic adenocarcinoma (1); pontocerebellar hypoplasia (1); portal hypertension (1); reproductive system diseases (1); schizencephaly (1); ZIKV infection (1).